RIPK3 (receptor interacting serine/threonine kinase 3)
Diseases named in the same sentence as RIPK3 in open-access papers (continued):
Sharing a sentence is not in itself a finding about the gene and the disease.
infection (continued). "Following infection, direct activation of RIPK3 mediates recruitment of FADD, RIPK1 and MLKL to drive both MLKL induced necroptosis and RIPK3/Caspase-8 mediated apoptosis." (PMID 36175538, 2023). "The results showed that the expression of p-RIPK1/RIPK1, p-RIPK3/RIPK3, and p-MLKL/MLKL was increased with H37Rv infection, while si-NR_003508 effectively reduced the expression of p-RIPK1/RIPK1, p-RIPK3/RIPK3, and p-MLKL/MLKL." (PMID 37175724, 2023). "Compared with WT BMDMs, the activation of CASP1/GSDMD/GSDME, CASP8/3/7, and RIPK3/MLKL in Mefv–/– and Zbp1–/– BMDMs decreased after infection with HSV1 or F. novicida, and completely inactive in Aim2–/– and Mefv–/–Zbp1–/– BMDMs." (PMID 36845112, 2023). "This demonstrates the critical role played by RIPK3 in phosphorylation of MLKL in human macrophages both constitutively and in response to infection and a smaller role for RIPK1 in response to infection." (PMID 37000865, 2023). "Since the discovery that ZBP1, via RIPK3, induces necroptosis during murine cytomegalovirus (MCMV) infection, its role in cell death during infection and embryonic development has been well established." (PMID 36268590, 2022). "Even though RIPK3 deletion restricts IAV-induced PCD, apoptosis activation is noted at a late stage of infection in these cells." (PMID 35587190, 2022). "The protein levels of RIPK3 in NIBV-infected renal cells and tracheal cells exhibited an increase (p < 0.05) at 1, 5, and 11 days post infection." (PMID 36016369, 2022). "Influenza A virus (IVA) infection is sensed by ZBP1, which activates RIPK3 and triggers MLKL-mediated necroptosis and FADD-mediated apoptosis." (PMID 35203445, 2022). "Knockdown of RIPK1, RIPK3, or MLKL in the background of infection with either RVA NCDV or DS-1 suppressed the expression of RVA proteins and titers." (PMID 34668777, 2022). "Infection with the bovine NCDV and human DS-1 RVA strains was shown to activate receptor-interacting protein kinase 1 (RIPK1), RIPK3, and mixed-lineage kinase domain-like protein (MLKL), the key necroptosis molecules in virus-infected cells." (PMID 34668777, 2022). "To accomplish this, we treated ZBP1+/+ and ZBP1−/− derived astrocytes with both a RIPK3 inhibitor (GSK872) and a pan caspase inhibitor (zVAD-FMK) following infection with HSV-1(MacIntyre), HSV-1(F), and HSV-1(F)-ICP6-RHIM Mut strains." (PMID 35549723, 2022). "Activation of ZBP1, i.e. upon infection with murine cytomegalovirus (MCMV) or IAV, leads to the recruitment of RIPK3 via RHIM interactions which mediates cell death." (PMID 36240069, 2022). "Enteropathogenic E. coli (EPEC) uses the type III secretion system effector EspL to degrade the RHIM‐containing proteins RIPK1, RIPK3, TRIF, and ZBP1/DAI leading to restricting necroptosis and pyroptosis during infection." (PMID 34977874, 2021). "Next, the RIPK3 and phosphorylation of MLKL definitely increased in the lungs of STING-/- mice during early infection compared to the control mice." (PMID 34135886, 2021). "In our study increased phosphorylation of RIPK1, RIPK3, and MKLK in ZIKV-infected astrocytes was detected early in the infection but only RIPK3 and MLKL phosphorylation remained throughout the infection and cell death." (PMID 33796483, 2021). "As expected, infection with lentivirus expressing sh‐JMJD3 led to decreased JMJD3 expression, whereas the infection of lentivirus expressing oe‐RIPK3 increased RIPK3 expression in LL29 cells." (PMID 33734576, 2021). "We therefore propose that RIPK3 platform activity-dependent and FADD-mediated apoptosis partially protect laboratory mice against IAV-infection in vivo." (PMID 33976111, 2021). "Western blot analysis showed that the phosphorylation of RIPK3 and MLKL was increased by PRV GD-WH infection in PK-15 cells at 12 and 24 hpi." (PMID 34149651, 2021).
infection (continued). "We found the expressions of mRNA expression of caspase-1, GSDMD, caspase-3, MLKL, RIPK3, NLRP3, IL-1β and IL-18 and of proteins cleaved caspase-1, GSDMD, cleaved caspase-3 and pMIKL in the macrophages of the three infection groups to be upregulated (P<0.05)." (PMID 34513732, 2021). "Knockdown of RIPK3 increased the survival rate of neuro2a cells after JEV infection with different PFUs and infection times." (PMID 32265853, 2020). "Studies have revealed that while Ripk3−/− and Mlkl−/−Fadd−/− mice are hypersusceptible to PR8 infection and display increased viral loads, following sublethal PR8 infection, Mlkl−/− mice exhibit no gross differences in susceptibility." (PMID 32260457, 2020). "RIPK3 also promoted or inhibited the propagation of virus in a cell death-independent manner during coxsackievirus B3 (CVB), IAV, and Zika virus (ZIKV) infections." (PMID 32265853, 2020). "Infection of cells with mutant MCMV that lacks M36 and M45 led to caspase 8 and RIPK3/MLKL activation and severely reduced viral replication." (PMID 30050058, 2019). "In this study, the mRNA level of RIPK1 and RIPK3 was enhanced in the lung tissues of patients killed by infection with H7N9 virus (P<0.05), as well as the protein level of RIPK1 and RIPK3 (P<0.05)." (PMID 31080811, 2019). "TNFα induces pathology in IOE infection, and TNFα is a driver of necroptotic cell death, a form of programmed necrosis involving RIPK1, RIPK3, and the effector protein MLKL." (PMID 30080899, 2018). "In order to explore the involvement of the axis RIPK1–RIPK3 on L. infantum replication in mice neutrophils, we performed infection assays in the presence of necrostatin-1 (Nec-1) or GSK’872, specific inhibitors of RIPK1 and RIPK3, respectively." (PMID 30154785, 2018). "In whole BM we found similar expression of RIPK3 and MLKL in WT and Ifnar1-/- mice during IOE infection." (PMID 30080899, 2018). "They demonstrate that during infection of macrophages with virulent M. tuberculosis, a complex of RIPK1/RIPK3/pro-caspase-8 translocates to the mitochondria." (PMID 28892415, 2017). "In aggregate, these results provide evidence that NC/99 infection activates parallel pathways downstream of the sensor protein DAI, the RIPK3–MLKL-dependent necroptosis pathway, as well as the RIPK3-caspase 8-mediated apoptosis pathway." (PMID 29203926, 2017). "To explore further, we performed RIPK3 co-immunoprecipitation and demonstrated an interaction between RIPK3 and MLKL following dl922-947 infection as well as an interaction between RIPK3 and adenovirus proteins." (PMID 29238045, 2017). "In contrast, viability upon MCMV‐M45mutRHIM infection was much higher in IFN‐treated Zbp1−/− primary MEFs, despite comparable expression of RIPK3 and MLKL." (PMID 28716805, 2017). "Additional studies are required to address this unique function of RIPK3 in regulating type I IFN responses, following infection with other strains of IAV or pathogens." (PMID 28410401, 2017). "Here co-immunoprecipitation experiments demonstrate that a RIPK3- and MLKL-containing complex forms following dl922-947 infection and that MLKL phosphorylation (and hence activation) is evident upon caspase inhibition." (PMID 29238045, 2017). "With longer infection time, CSFV could obviously increase RIPK3 and ZBP1 mRNA levels in PBMCs compared with the control, whereas it suppressed MLKL mRNA levels at 60 h of infection." (PMID 38100396, 2024). "We found that the inflammation/infection-induced HSPC necroptosis and BM failure in Casp8−/− mice can be completely prevented by Ripk3 deletion; however, the HSC self-renewal defects of Casp8−/− HSCs is mediated by Ripk1-Tbk1-Ifnβ signaling independent of Ripk3." (PMID 38637559, 2024). "As an essential component of host defense against infection, necroptosis is a novel highly regulated mode of cell death that is mediated by signaling complexes containing receptor-interacting protein kinase 1 (RIPK1) and RIPK3." (PMID 38100396, 2024).
infection (continued). "To further confirm whether RIPK3 promoted ISG expression in these cells, we acutely isolated cerebellar granule cell neurons ex vivo following intracranial LGTV infection." (PMID 38011306, 2023). "In contrast to our observations with RIPK3 inhibition, we observed increased phagolysosomal fusion when combining 666–15 with NSA compared to MDMs treated with 666–15 alone (blue versus maroon bars) at 30 and 90 min post-infection." (PMID 37000865, 2023). "Differences in ISG expression between regional neuron types were not driven by differential rates of cell death, as pharmacologic blockade of RIPK3 did not impact viability of either neuron type following LGTV infection." (PMID 38011306, 2023). "A range of diverse non-necroptotic functions have been attributed to RIPK3, including a central role in cytokine and chemokine initiated immune control of infection, and RIPK3-dependent but MLKL-independent mechanisms have been implicated in immune defense." (PMID 36792599, 2023). "The significance of necroptosis as a host defence mechanism against infection has been primarily defined by studies investigating the role of RIPK3 rather than MLKL." (PMID 36792599, 2023). "Infection of mice with their natural pathogen, LCMV, may provide opportunity to examine RIPK3’s role outside of its necroptotic function." (PMID 36792599, 2023). "Consistent with our in vivo findings, blockade of RIPK3 in cerebral cortical neurons did not impact chemokine expression following LGTV infection." (PMID 38011306, 2023). "Casp1/11–/–Casp8+/–Ripk3–/– mice retain Caspase-8 function downstream of both NLRC4 and TNFα and based on our previous experiments with Casp1/11–/– mice, we expected that these mice would be resistant to infection." (PMID 36645406, 2023). "Following infection with IAV, the NLRP3 of the host activates, and then a large number of pro-inflammatory cytokines secretes, while in the Ripk3-/- Casp8-/- Ripk1-/- and Zbp1-/- bone marrow-derived macrophages (BMDMs), pro-inflammatory cytokines are no longer secreted." (PMID 37771585, 2023). "Following infection with HSV1 by corneal inoculation, 100% of Ripk3K51A/K51A mice survived, mirroring the survival of HSV1-infected WT mice but unlike HSV1-infected Ripk3-/- mice that showed increased HSE susceptibility." (PMID 36121858, 2022). "Since loss of the Zα—Z-nucleic acid binding domain—of E3 leads to activation of RIPK3, and since ZBP1 is highly IFN-inducible in L929 cells, we hypothesized that ZBP1 was likely a sensor detecting VACV E3LΔ83N infection." (PMID 35203445, 2022). "Interestingly, recent studies also uncovered mechanisms in which RIPK3 triggers RIPK1-dependent apoptosis, often as part of the induction of multiple regulated cell death pathways in parallel in response to infection." (PMID 36040212, 2022). "Deletion of RIPK3 is not sufficient to protect cells from death during this infection, while the combined deletion of caspase-8/RIPK3 does prevent cell death." (PMID 35563804, 2022). "Moreover, H37Rv infection increased the expression of the molecules involved in the necroptotic pathway, such as ASK1, p-38, RIPK1, RIPK3, and caspase-8, while H37Ra increased caspase-8 and decreased RIPK3 at the transcriptional level." (PMID 35631013, 2022). "It seems that Ripk3−/− mice are not able to reduce the pathogen burden when it reaches a certain threshold, and eventually succumb to the infection." (PMID 35351865, 2022). "We found that non-vaccinated and vaccinated Ripk3−/− mice display reduced immune cells infiltration in the lungs and accumulate more dying cells post infection compared to their wild type littermates." (PMID 35351865, 2022). "We again saw an increased parasite burden in infected RIPK3−/− mice, but due to the variability of the infection in RIPK3−/− mice, this difference was not significant." (PMID 33526566, 2021).
infection (continued). "At 6 and 12 h post-infection, the mRNA expression levels of caspase-3, caspase-1, GSDMD, RIPK3, MLKL, NLRP3, IL-1β, and IL-18 were upregulated in RAW264.7 macrophages infected with either E. faecalis CA1, CA2, or OG1RF strains compared to the levels in the control group." (PMID 34513732, 2021). "To evaluate the temporal aspects of PCD suppression by vIRA, vICA, vMIA and vIBO, we compared the parental virus to M45mutRHIM (inducer of RIPK3-dependent necroptosis), ∆M36 (inducer of CASP8-dependent apoptosis), and ∆M38.5/M41.1 viruses during infection of WT macrophages." (PMID 34578288, 2021). "Immediately following the infection of macrophages, MCMV faces RIPK3 in the cytoplasm." (PMID 34578288, 2021). "Mice lacking necroptosis components RIPK3 or MLKL survived similarly to WT mice during infection with B. thailandensis, suggesting necroptosis is not required to control B. thailandensis." (PMID 34154417, 2021). "Similar to the phenotype observed in Casp8/Ripk3/Casp1/11−/− mice, B. thailandensisvgrG5ΔCTD infection was also attenuated in mice lacking caspase-1/11 or GSDMD." (PMID 34154417, 2021). "WT and Ripk3−/− mice succumbed to infection at similar rates, and caspase inhibition did not impact outcome." (PMID 33024046, 2020). "Mice lacking necroptosis alone (Mlkl–/– mice) or those with combined deficiency in pyroptosis and necroptosis (Casp1–/–;Casp11–/–;Casp12–/–;Ripk3–/– mice) had no defects in bacterial control until at least 3 weeks post-infection." (PMID 32735843, 2020). "The combined lack of caspase-8-mediated apoptosis and RIPK3-driven necroptosis did not have significant impact on Salmonella titers 3 weeks post-infection." (PMID 32735843, 2020). "Similarly, siRNA‐mediated knockdown of RIPK1 or RIPK3 in HT29 cells infected with ΔospD3 decreased levels of phosphorylated MLKL and cytotoxicity to the levels observed in WT infection." (PMID 32657447, 2020). "After 18 h of infection with noninvasive S. Typhimurium, caspase inhibition resulted in significantly higher levels of death in WT macrophages but not Ripk3−/− macrophages." (PMID 33024046, 2020). "Akin to RIPK3 deficiency, a recent study reported that mice lacking ZBP1 were hypersusceptible to PR8 infection with elevated viral loads." (PMID 32260457, 2020). "Similar to infection with MCMV, ZBP1 functions as the upstream sensor of IAV RNA to activate RIPK3." (PMID 30050058, 2019). "Infection by some RNA viruses, including vesicular stomatitis virus (VSV), Sendai virus, and influenza virus, induces NLRP3 inflammasome activation, and the silencing of RIPK1 and RIPK3 leads to a severe reduction in inflammasome activation." (PMID 31509938, 2019). "Consistent with the notion that HCMV does not target ZBP1 or RIPK3, super-infection with M45 RHIM mutant MCMV in HCMV-infected cells no longer sensitize the cells to necroptosis." (PMID 30050058, 2019). "We found that the bacterial burdens in the lungs of Ripk3−/− mice were indistinguishable from their WT counterparts 10 days post-infection." (PMID 29892302, 2018). "Within the HSPC and HSC populations, we observed a greater proportion of Ripk3Δintron2 cells relative to WT cells, even in the absence of infection, suggesting RIPK3 impairs HSC and HSPCs in the context of transplantation." (PMID 30080899, 2018). "However, during infection type I IFNs mediated HSPC death by reducing caspase 8 expression and activity, which correlated with reduced RIPK1 and RIPK3 cleavage in the BM." (PMID 30080899, 2018). "We also did not observe any difference in the ability of Ripk3−/− BMDMs to express iNOS upon infection." (PMID 29892302, 2018). "Whether the increased RIPK1, RIPK3 and MLKL activation marks a typical necroptotic, lytic event during infection or if KPn utilizes the necroptosis machinery to modulate cellular functions in its favor, or a combination of both, requires further investigation." (PMID 30273394, 2018).
infection (continued). "There was clear evidence of MLKL phosphorylation 72 h following dl922-947 infection in the presence of zVAD.fmk but not at 24 or 48 h, and the effect of zVAD.fmk was partially rescued by the RIPK3 inhibitor GSK2791840B." (PMID 29238045, 2017). "We report here that RIPK3 is dispensable for RLR-driven transcriptional activation of type I IFNs and other antiviral genes in murine fibroblasts, but plays a modest and selective role in post-translational production of IFN-β upon infection by IAV." (PMID 27391363, 2016). "Ripk3-/-Casp8-/- mice exhibit severely diminished cytokine responses following infection by a number of gram-negative bacterial pathogens, including Yersinia, in contrast to Ripk3-/- mice, which have no discernible defect." (PMID 27737018, 2016). "Although EspL cleaved RIPK1 and RIPK3 to generate the expected p61 and p50 fragments, LDH release, apoptotic caspase processing and cleavage of the fluorogenic caspase substrates were comparable between C. rodentium and ΔespL infection in macrophages and CMT-93 cells." (PMID 40128366, 2025). "Furthermore, robust phosphorylation of the necroptotic molecules MLKL and RIPK3 did not occur in Aim2–/– pBMDMs upon MPXV infection." (PMID 41225161, 2025). "Localized delivery of RIPK1/RIPK3/MLKL pathway inhibitors may confine necroptosis suppression to the infection site, thereby reducing local inflammation without compromising systemic immune defenses." (PMID 41142308, 2025). "The results showed that the levels of p-RIPK3 and p-MLKL were significantly increased in the ZBP1 overexpression PTCs comparing with the vector control transfected cells (Vec) during PPV infection, while the expression levels of RIPK3, MLKL, and Caspase-8 did not significantly change." (PMID 39614405, 2024). "Intriguingly, ablating Gsdmd on a Casp8–/–Ripk3–/– background did not reproduce the C. rodentium lethality phenotype as obtained after Casp1/11 deletion, as all Casp8–/–Ripk3–/–Gsdmd–/– mice survived the infection." (PMID 37080966, 2023). "In both cell lines, there is expression of RIPK3, and this expression is not decreased upon infection by the viruses, suggesting that RIPK3 is still present in infected cells and blockade of p-MLKL expression was not caused by downregulation of RIPK3 expression." (PMID 36768641, 2023). "Similarly, Casp1/11+/–Casp8–/–Ripk3–/– mice retain the ability to recruit Caspase-1 to NLRC4 and to initiate cell death via Caspase-11 and should also thus be resistant to infection." (PMID 36645406, 2023). "Our data suggest that RIPK3-dependent necroptosis was inhibitory to ZIKV replication, indicating that this cell death could be beneficiary to the host even though infected astrocytes died of the necroptotic signaling during the infection." (PMID 33796483, 2021). "However, unlike ZBP1−/− mice, the RIPK3−/− mice had significantly improved survival after oral infection with both T. gondii oocysts and brain tissue cysts." (PMID 33526566, 2021). "Western blot analysis of an infection time course showed a pronouncedly increased abundance of a key protein required for induction of necroptosis, receptor-interacting serine/threonine-protein kinase 3 (RIPK3), in the absence of HPSE." (PMID 33621216, 2021). "Interestingly, these experiments also revealed that infection with Chlamydia did not prevent RIPK3 or MLKL activation induced by TSZ in HT29 cells and rather enhanced resulting necrotic cell death." (PMID 30375511, 2019). "Receptor-interacting protein kinase 3 deficiency did not result in any defects in terms of Mtb internalization or activation of antimicrobial defenses, suggesting that during infection in vitro, RIPK3 does not impact on the capacity of macrophages to respond to intracellular Mtb." (PMID 29892302, 2018). "Indeed, we noted a very marginal increase in bacterial numbers and inflammation 4 weeks post-infection with Mtb in mice lacking RIPK3." (PMID 29892302, 2018).